WNT5A (Wnt family member 5A)
Diseases named in the same sentence as WNT5A in open-access papers (continued):
Sharing a sentence is not in itself a finding about the gene and the disease.
colorectal cancer (continued). "Several studies show that ligand Wnt5a often activates the Wnt–Ca2+ pathway in cancer cells and higher expression of Wnt5a suppresses breast and colorectal cancer (CRC)." (PMID 31684152, 2019). "In colorectal cancer (CRC), loss of WNT-5A is frequently observed and associated with poor prognosis and survival." (PMID 26514730, 2016). "WNT5A is silenced in most colorectal cancer cell lines and nasal NK/T-cell lymphoma due to promoter methylation." (PMID 26316480, 2015). "Wnt3a and wnt5a are highly expressed in colorectal cancer both in primary and metastatic sites with a higher than 50% concordance rate." (PMID 24564183, 2014). "Other studies reported that Wnt5a had the ability to inhibit proliferation, migration and invasiveness in thyroid tumors and colorectal cancer cell lines." (PMID 23844260, 2013). "In contrast, some reports indicate that in view of its ability to inhibit cell proliferation, motility, or invasion in thyroid tumor and colorectal cancer cell lines, Wnt-5a acts as a tumor suppressor." (PMID 24351810, 2013). "On the other hand, both canonical and non-canonical Wnt signalling, though mutually antagonistic, appear to act complementary in different stages of colorectal cancer development, Wnt5a being upregulated in the later invasive stage." (PMID 22384081, 2012). "We quantified promoter methylation levels of the Wnt5a gene in 545 colorectal carcinomas from Ontario and 687 colorectal carcinomas from Newfoundland." (PMID 21587258, 2011). "A large number of studies have indicated that Wnt-5a commands a tumour-suppressing effect, and it was shown to be downregulated in a number of different cancers such as colorectal cancer, neuroblastoma, ductal breast cancer and leukaemias." (PMID 19603030, 2009). "This tumour-suppressive role was further evidenced by studies that reintroduced Wnt-5a into SW480 colorectal cancer or thyroid cancer FTC-133 cell lines resulting in decreased invasion, migration, colonogenicity and proliferation." (PMID 19603030, 2009). "It is possible, however, that epigenetic regulation is involved, as methylation of the Wnt-5a promoter was identified in a large proportion of lymphoblastic leukaemia patients and in colorectal cancer patients." (PMID 19603030, 2009). "Wnt5a triggered the M2 polarization of tumor-associated macrophages by modifying CaKMII-ERK1/2-STAT3-mediated IL-10 production, leading to the induction of tumor growth and the metastasis of colorectal cancer." (PMID 40427533, 2025). "In oral squamous cell carcinoma, miR-146b inhibition suppressed migration, cell proliferation, and invasion via binding and downregulating HBP1 expression and in the colorectal cancer miR-576-5p-targeted Wnt5a-mediated Wnt/β-catenin signaling pathway by inducing epithelial-to-mesenchymal transition." (PMID 34804161, 2021). "WNT5A was shown to inhibit migration of the SW480 colorectal cancer cell line, which lacks WNT5A." (PMID 26978652, 2016). "In addition, WNT5A inhibits proliferation of leukemia, lymphoma and colorectal carcinoma cells, demonstrating its tumor suppressive function in these cancers." (PMID 24260410, 2013). "We demonstrate that WNT5A mutations correlate with outcomes in colorectal cancer and find that, contrary to expectations, mutations do not impact WNT ligand binding to their respective receptors but instead appear to influence the dynamics and flexibility of the proteins." (PMID 40165370, 2025). "However, whether Wnt5a regulates the polarization and biological function of TAMs in colorectal cancer (CRC) is incompletely understood." (PMID 32228612, 2020). "Previous studies have shown that Wnt5a is downregulated in certain malignancies including colorectal cancer (protein expression), neuroblastoma (mRNA levels), invasive ductal breast carcinomas (protein expression) and leukemias (mRNA levels), indicating a tumor suppressing effect of Wnt5a." (PMID 22039506, 2011).
colorectal cancer (continued). "It has previously been demonstrated by at least two independent meta-analyses that in contrast to the prognostic effect of WNT5A expression, patients with elevated expression of the LGR5 protein in their colorectal cancer tissue had poor overall survival." (PMID 37998393, 2023). "In colorectal cancer (CRC), altering Wnt5a expression can influence several cellular processes of tumor cells, including proliferation, differentiation, migration, invasion, and metastasis." (PMID 34603445, 2021). "Although the roles of Wnt5a on tumor cells have been well studied in multiple solid tumors 11, 13, 14, little is known about the interaction between Wnt5a and TME in colorectal cancer (CRC)." (PMID 32140070, 2020). "Using colorectal cancer data, we showed that SMARCD3 expression was positively correlated with WNT5A, TGF-β and p-MAPK14, which were consistent with previous reports." (PMID 33125346, 2020). "The KEGG pathways “colorectal cancer” and “pathways in cancer” were enriched in the downregulated PM cluster and included Frizzled receptors FZD1, 2, 4, 6, and 7 and signaling protein WNT5a, all key members of the wnt pathway." (PMID 24906157, 2014). "In colorectal cancer, HADH has been implicated in non-canonical Wnt signaling, regulating tumor proliferation and metabolic activity via the Wnt5a/b-Ror2/Dvl2-ATF2/4 axis." (PMID 40821775, 2025). "In contrast, a few studies showed that Wnt5a had no or weak expression in colorectal cancer and mainly played a role in tumor suppression." (PMID 32228612, 2020). "According to literature data, high expression of WNT1 genes and low expression of noncanonical WNT5A correlating with cytoplasmic and nuclear β-catenin are observed in colorectal cancer; all these three characteristics are indicative of the shortened recurrence-free survival." (PMID 37345102, 2023). "However, the roles of wnt3a and wnt5a in colorectal cancer (CRC) have not been thoroughly studied." (PMID 24564183, 2014).
glioma (47 papers, 2012 to 2026). A benign or malignant brain and spinal cord tumor that arises from glial cells (astrocytes, oligodendrocytes, ependymal cells). "The survival analysis revealed that the higher mRNA expression levels of WNT5A was significantly associated with shorter OS in patients with glioma." (PMID 32181818, 2020). "In silico studies, using GB samples from the TCGA and immunohistochemistry of human biopsies (TMAs), have shown that gliomas have high expression of WNT5a and that this aberrant expression is associated with the presence of immune cells." (PMID 30123112, 2018). "As ligands that activate the Wnt/β-catenin signaling pathway, WNTs are widely implicated in the development of glioma, and clinical data show that expression levels of WNT5A, WNT3A and WNT1 are closely correlated with the overall survival of patients with glioma." (PMID 41184253, 2025). "WNT5A has been shown to be upregulated in glioma and is associated with poor overall survival." (PMID 34957471, 2021). "The mRNA levels of WNT5A was positively associated with the WHO grade of glioma." (PMID 32181818, 2020). "In addition, WNT5A was found to induce rapid growth and migration of glioma and associated with the presence of tumor-associated microglia." (PMID 32181818, 2020). "We can just guess WNT5A may cause classic pathways activated in glioma." (PMID 32181818, 2020). "A recent study also showed that Wnt5a expression was positively correlated with the presence of microglia/monocytes in human gliomas and increased expression of human leukocyte antigens (HLA) genes, which are associated with a strong pro-inflammatory signature in the human glioma microenvironment." (PMID 27571105, 2016). "The observed effect of low taurine on Wnt5a promoter methylation suggests a novel mechanism by which glioma cells regulate their invasive behaviour." (PMID 40373156, 2025). "Recent studies have shown that hypotaurine promotes glioma U251 cell invasion by epigenetically regulating Wnt5a expression (Wnt5a, a glycoprotein that functions as a tumor suppressor or promoter, depending on the cancer type)." (PMID 41154707, 2025). "This study investigates the role of hypotaurine, a sulfur-containing amino acid derivative, in glioma cell invasion, with a specific focus on its impact on Wnt5a gene expression and promoter methylation." (PMID 40373156, 2025). "A Wnt5a knockdown inhibited the activity of the GSK3β/β-catenin pathway related to glioma-derived endothelial cell angiogenesis." (PMID 41031155, 2025). "This study demonstrates that hypotaurine promotes glioma cell invasion by epigenetically regulating Wnt5a expression through promoter methylation." (PMID 40373156, 2025). "Further functional analysis confirmed that H19 can directly target miR-342 to promote the expression of Wnt5a and activate the β-catenin signaling pathway to promote angiogenesis in glioma." (PMID 38967893, 2024). "In both GBM and low-grade glioma (LGG), the expression of Wnt5a was significantly increased in glioma tissues compared with normal tissues (p < 0.05)." (PMID 38699473, 2024). "H19 is highly expressed in glioma and directly targets miR-342 to upregulate Wnt5a, a target gene of miR-342, to activate the Wnt5a/β-Catenin pathway and suppress tumor apoptosis." (PMID 38355574, 2024). "Wnt5a, a member of the WNT family, has been previously demonstrated to induce rapid glioma growth and migration while also being associated with the survival of tumor-associated microglia." (PMID 38699473, 2024). "Through RT-qPCR, it was found that lncRNA H19 and Wnt5a are significantly upregulated in glioma tissues and cells, while miR-342 is downregulated." (PMID 38967893, 2024). "Experimental knockdown of WNT5A resulted in the suppression of angiogenesis and tumor progression and decreased the stimulation of glioma stem cells to differentiate into endothelial cells." (PMID 38275375, 2023).
glioma (continued). "Wnt5a enhances glioma cell migration by regulating the expression of MMP-2, which is involved in ECM degradation." (PMID 36675073, 2023). "A bioinformatics analysis of all 19 WNT ligands in human gliomas revealed an overexpression of WNT5A and a decreased expression of WNT10B in tumors compared to normal tissue." (PMID 36814601, 2023). "Wingless-related integration site family member 5A (WNT5A) has been shown to be involved in endothelial differentiation during embryogenesis but also in the transition of glioma stem cells to endothelial cells." (PMID 38275375, 2023). "In glioma, circKIF4A is reported to promote Wnt5a expression by sponging miR-139-3p, thus promoting cell migration and invasion and disease progression." (PMID 36230873, 2022). "It was found that lncRNA SOX2OT reduced the methylation level of SOX2 by interacting with ALKBH5, thus improving the SOX2 expression and activating the Wnt5a/β-catenin signaling pathway to promote TMZ resistance in glioma cells." (PMID 35912271, 2022). "Knockdown of miR-342 in turn promoted Wnt5a and β-catenin expression to positively regulated the Wnt5a/β-catenin signaling axis and glioma cell proliferation." (PMID 35912271, 2022). "WNT5A/GSK3β/β-catenin signaling played a pivotal role in the angiogenesis of glioma-derived endothelial cells." (PMID 35494062, 2022). "The group found that the most invasive gliomas are characterized by Wnt5a overexpression associated with tumor-promoting stem-like characteristics (TPC); indeed, inhibition of Wnt5a in mesenchymal GBM TPC suppresses their infiltration capacity." (PMID 34948224, 2021). "H19 silencing reversed glioma cell growth and metastasis by regulating the miR-342-mediated Wnt5a/β-Catenin signaling pathway with decreased levels of vascular endothelial growth factor A (VEGFA), MMP9, Wnt5a, and β-catenin." (PMID 34977037, 2021). "Consistent with previous reports, our study also found that Wnt5a level was significantly increased in glioma cell lines and tissues." (PMID 32268875, 2020). "Higher mRNA levels of WNT5A and WNT16 were significantly associated with poor OS in patients with glioma." (PMID 32181818, 2020). "CCLE analysis was also revealed that WNT5A mRNA expression was significantly up-regulated in glioma compared with other human cancers." (PMID 32181818, 2020). "In this study, we found that circKIF4A and Wnt5a were over-expressed, and miR-139-3p was down-expressed in glioma cell lines and tissues." (PMID 32268875, 2020). "WNT5A played role in glioma by taking part in WNT/Ca2+pathway and the canonical pathway, however, WNT10B was only ligands of canonical pathway." (PMID 32181818, 2020). "In the de Novo pathway of glioma occurrence, two crucial oncogenes (EGFR and MDM2) and two important tumor suppressors (PTEN and IKN4a/ARF) were found to be closely correlated with WNT5A in glioma." (PMID 32181818, 2020). "Wnt5a is one of the important members of the Wnt family, and more and more studies have shown that changes in Wnt5a expression are closely related to the progression of glioma." (PMID 32268875, 2020). "Obviously, it is of great significance to explore the molecular mechanisms of Wnt5a-mediated β-catenin signaling pathways regulating glioma." (PMID 32268875, 2020). "To investigate the roles of circKIF4A, miR-139-3p and Wnt5a in glioma, we first detected the expression of circKIF4A, miR-139-3p and Wnt5a in 32 pairs of glioma and adjacent normal tissues." (PMID 32268875, 2020). "Spearman correlation analysis was performed to calculate the correlation among circKIF4A, miR-139-3p, and Wnt5a levels in glioma samples." (PMID 32268875, 2020). "As WNT5A and WNT10B were the most correlated with glioma prognosis and clinicopathology, we analyzed the 50 most frequently altered neighbor genes of WNT5A and WNT10B in glioma and constructed integrated networks using String." (PMID 32181818, 2020).
glioma (continued). "The results demonstrated that the expressions of circKIF4A and Wnt5a were increased, and miR-139-3p level was decreased in glioma cell lines compared to NHA control cell." (PMID 32268875, 2020). "circKIF4A was overexpressed in glioma, and knockdown of circKIF4A suppressed glioma progression via miR-139-3p/Wnt5a axis." (PMID 32268875, 2020). "Our results indicated that mRNA expressions of WNT5A and WNT10B were significantly differentially regulated in glioma compared with NB tissues, and associated with pathology and grade of glioma." (PMID 32181818, 2020). "In terms of mechanism, we demonstrated that low expression of circKIF4A suppressed GICs self-renewal and glioma progression via modulating miR-139-3p/Wnt5a/β-catenin axis." (PMID 32268875, 2020). "The survival analysis revealed that the higher expressions of WNT5A and WNT16 were associated poor overall survival (OS) in patients with glioma." (PMID 32181818, 2020). "Compared with normal ones, a higher level of circKIF4A and Wnt5a were detected, and a lower level of miR-139-3p was detected in glioma tissues." (PMID 32268875, 2020). "circKIF4A and Wnt5a were up-regulated and miR-139-3p was down-regulated in both glioma cells and tissues." (PMID 32268875, 2020). "MiR-129-5p expression levels were downregulated and inversely correlated with Wnt5a expression levels in CGGA glioma patients." (PMID 29531296, 2018). "The expression of Wnt5a and miR-129-5p in 24 glioma specimens were observed to be inversely correlated." (PMID 29531296, 2018). "Wnt5a expression is higher in glioma than that in normal brain and is correlated with WHO histological grade progression." (PMID 29531296, 2018). "Here, we demonstrate that Wnt5a is targeted by miR-129-5p, whose expression is inversely correlated with Wnt5a in glioma." (PMID 29531296, 2018). "The glioma groups with high expression of WNT5a presented high levels of CX3CR1, connexin 43 (CX43), CD163, and IBA-1, suggesting that the GB-infiltrating microglial cells are activated, which represent the M2-like phenotype." (PMID 30123112, 2018). "The role of Wnt5a in promoting proliferation and migration of cells has been demonstrated in gliomas, in vitro." (PMID 29531296, 2018). "The expression of Wnt5a mRNA was significantly higher in 24 gliomas than that in 6 normal brain tissues." (PMID 29531296, 2018). "Among Wnt ligands, receptors and co-receptors, we found that FZD3, ROR2, and Wnt5a regulate FZD6 overexpression-induced phenotypes in glioma spheres." (PMID 27698350, 2016). "This indicates that Wnt5a, at least in part, is responsible for the characteristic inflammatory profile of the glioma." (PMID 27571105, 2016). "The role of Wnt5a in glioma development needs to be further investigated." (PMID 40373156, 2025). "Consequently, we postulate that hypotaurine exerts its inhibitory effect on demethylase activities, resulting in Wnt5a promoter hypermethylation and enhanced invasion ability of glioma cells." (PMID 40373156, 2025). "Many studies on gliomas tended to view Wnt5a as an invasion promoter." (PMID 40373156, 2025). "In gliomas, our findings suggest that Wnt5a expression is epigenetically regulated by hypotaurine, which may influence its functional role." (PMID 40373156, 2025). "Moreover, the protein expression of Wnt5a was also increased in glioma cell lines, compared with that in NHA cells." (PMID 32268875, 2020). "Finally, KEGG pathway enrichment analysis revealed WNT5A and neighbor genes were essential in the occurrence glioma." (PMID 32181818, 2020). "Subsequently, it was proved that Wnt5a was the target gene of miR-139-3p in glioma cells." (PMID 32268875, 2020). "Among the 19 WNTs, WNT5A is the most commonly studied in glioma, particularly GBM." (PMID 32181818, 2020). "For instance, miR-30a represses glioma progression via repressing Wnt5a." (PMID 33103739, 2020).